NF1 (neurofibromin 1)
Diseases named in the same sentence as NF1 in open-access papers (continued):
Sharing a sentence is not in itself a finding about the gene and the disease.
tumor (continued). "Prospective studies, such as the ongoing NF1-LGG and NF1-OPG natural history studies, will be needed to confirm tumor location and extent of disease as prognostic factors in NF1-LGG." (PMID 40296988, 2025). "Here, we demonstrate an inhibitory effect of NF1-GRD (GAP-related domain, residues 1198–1509) fused with RAS-CAAX motif on tumor cell growth and ERK signaling in NF1-MPNST and further prove the growth dependency of NF1-MPNST cells on CRAF and BRAF." (PMID 41023593, 2025). "Further refinement by integrating a random 7mer peptide into the VR-VIII loop enhanced NF1 tumor targeting, resulting in the vector K55-GRDC24, which demonstrated therapeutic efficacies in NF1 models." (PMID 41022755, 2025). "In addition, in our unselected cohort, many PGVs are identified in genes such as BRCA1, MSH6, PMS2, and NF1, which are crucial not only for germline follow-up but also for selecting appropriate therapies, particularly immune-based or targeted treatments, as observed in other tumor types." (PMID 41168197, 2025). "pNF1 tumors consist of SC-derived tumor cells (Nf1−/−) and the tumor microenvironment (TME), including cellular (e.g., fibroblasts, endothelial cells, and inflammatory cells; Nf1+/−) and patho-chemical components resulting from hypoxia and acidosis." (PMID 40862755, 2025). "The tumor lineage and aggressive potential was confirmed by extensive genetic testing revealing a high tumor mutational burden and pathogenic mutations in TERT, NRAS, and NF1, alongside alterations in PBRM1 and FAT1, which may contribute to the tumor's unique morphology." (PMID 40125165, 2025). "Among the most widely used and data-richest platforms for NF1-related research are the Neurofibromatosis Therapeutic Acceleration Project (NTAP), the Children’s Tumor Foundation (CTF) Synodos, and the National Cancer Institute—Genomic Data Commons (NCI-GDC)." (PMID 41463204, 2025). "When visual acuity is reduced on sequential ophthalmologic assessments, children with NF1-OPG are typically treated with chemotherapy, and therapeutic success is based on both tumor shrinkage and vision stabilization/improvement." (PMID 41497446, 2025). "That year, the NF1 gene was localised to chromosome 17q using family linkage and the NF2 gene to 22q using tumour analysis and family linkage." (PMID 41160189, 2025). "While some of these truncations, such as NF1 in UCEC and MAP2K4 in BRCA, were often accompanied by lower-than-median mRNA expression in their respective tumor cohorts, their impacts were strikingly observed at diminished protein expression levels." (PMID 39775839, 2025). "In this study, single-agent tovorafenib had little anti-proliferative effect in NF1-LOF tumor cell lines, yet the combination of pimasertib with either tovorafenib or TAK-632 exhibited synergy in NF1-LOF tumor models in vitro." (PMID 40111124, 2025). "Fibroblasts (Nf1+/−), the most abundant cell type in the TME, are known to significantly contribute to pNF1 formation, but their precise role in the subsequent tumor progression is poorly understood." (PMID 39061138, 2024).
tumor (continued). "Seven tumors had BRAF mutation (one was a rare mutation: BRAFp.G469A), six had BRAF fusion, and two were empirically treated; one (#10) had NF1 and one (#14) with DLGNT had small tumor biopsy insufficient for NGS testing." (PMID 39399174, 2024). "An autosomal dominant pattern of inheritance, tumor development at an early age, and multiple lesions are common features described for genodermatoses, such as BSS and NF-1." (PMID 38673513, 2024). "However, there was no clinical evidence of NF1 nor a germline or tumor mutation in the NF1 gene." (PMID 39200173, 2024). "Tumors with BRAF mutation were treated with dabrafenib and trametinib was added after tumor progression, while tumors with BRAF fusion, NF1 or DLGNT were treated with trametinib." (PMID 39399174, 2024). "Analysis of region 3 investigating cycling (K) and noncycling (T) tumor cells revealed immense cellular heterogeneity, especially in the progenitor tumor cell phenotype and EGFR, NF1, and PDGFRA gene expression." (PMID 38077210, 2023). "Using these murine PDGFB-driven (PDGFB mGBM) and Nf1-silenced (Nf1 mGBM) GBM models that show differential myeloid recruitment, we investigated how IL-1α and IL-1β individually contribute to tumor development in vitro and in vivo." (PMID 37733448, 2023). "Together, these results suggest that downregulation of NF1 plays an essential role in PDE4DIP-promoted overactivation of RAS/ERK/AKT signaling and CRC tumor growth." (PMID 37355626, 2023). "Taken together, these data indicate that PKCε activation plays an essential role in PDE4DIP-promoted NF1 degradation and CRC tumor growth." (PMID 37355626, 2023). "Moreover, the in vitro sensitivity of the Nf1-ko endothelial cell proliferation and the normalization of the vascular morphogenesis following treatment with low-dose rapamycin suggests that anti-tumor drugs may be effective for treating certain types of vascular dysfunctions in NF1 patients." (PMID 36980803, 2023). "Studies have shown that serial VA changes do not reliably identify tumor progression and tumor progression does not correlate well with decreased VA, while better initial VA, older age, absence of post-chiasm tumor and presence of NF1 were associated with improved or stable VA outcomes." (PMID 37519788, 2023). "In NF1+/-GFAPCKO mice, the formation of optic glioma only in NF1+/- mice with astroglial NF1 inactivation suggested that this tumor required microenvironment composed of cells heterozygous for NF1 mutation." (PMID 38318325, 2023). "Our results demonstrated that NF1 was significantly upregulated in GBC and functioned as an oncogene, promoting tumor growth and migration." (PMID 37147639, 2023). "In vivo combination of trametinib with BCL-2 inhibitors led to tumor inhibition in NRAS-mutant and NF1-deleted xenografts." (PMID 36895472, 2023).
tumor (continued). "We have previously demonstrated that inhibition of both ER and RAS signaling by fulvestrant and binimetinib induces tumor regression in WHIM16, which was identified previously as an NF1-depleted ER+ PDX model as measured by RNA-seq and Western blot analysis." (PMID 37501682, 2023). "Our findings suggest that NF1 is the downstream transducer of PDE4DIP signaling and that the growth advantage of tumor cells with high PDE4DIP expression is most likely conferred by overactivation of oncogenic RAS signaling due to loss of NF1." (PMID 37355626, 2023). "Like patients with NF1-OPG, the Nf1OPG mice exhibit thinner retinal nerve fiber layers as measured by OCT and reduced VEP amplitudes than the non-tumor controls." (PMID 37891793, 2023). "For example, the inactivation of NF1—a positive regulator of KRAS GTP to GDP transition—should shift KRAS proteins into their GTP-bound state and increase tumor number and/or growth in the KRAS G12C-, KRAS G12D- and EGFR-driven tumors." (PMID 37828026, 2023). "The hot genes with the most positive signal events in the normal-specific group were RBPJ, PFKFB3, CAMK1D, ACACB, and WWOX, whereas the hot genes in the tumor-specific group were SLC35F3, PCDH7, NF1, and RAB27B." (PMID 36895481, 2023). "In the current study, we demonstrate that combinational treatment with lovastatin and an FTI dendrimer suppresses the growth of established NF1 MPNST sciatic nerve xenografted tumors, a Ras-driven tumor type that currently has very limited therapeutic options." (PMID 38201517, 2023). "The relevance of tumor biology was evaluated via the KIAA1549-BRAF fusion status for progressive OPG, which showed a reduced PFS compared to NF1 OPG." (PMID 36551572, 2022). "A multivariate analysis was performed including tumor and nodal classification, grade, PAM50 subtype, NF1, KRAS, RAF1, and JUN alterations." (PMID 36358725, 2022). "The median tumor extension score was 6 (IQR 1.25; 10) in NF1 + OPG and 11 (IQR 9; 11) in spOPG patients, implying that spOPGs involve more segments of the optic pathway." (PMID 34994964, 2022). "Interestingly, the magenta module highly enriched the signature genes for stem-like tumor cells, which is consistent with cancer stem cell theory that argues stem-like tumor cells originate from neural crest stem cells and serve as a constitutive force to drive NF1 PN tumorigenesis." (PMID 35741605, 2022). "Next, we examined differential gene expression when the HP primary tumor and metastatic samples were subdivided into their particular genomic subtypes (BRAF, RAS, triple WT and NF1)." (PMID 35560144, 2022). "In fact, the loss of function caused by NF1 gene mutation may prolong the activation time of the Ras dependent signal pathway, and, in addition, may cause abnormal signal expression which is different from the classic BRAF mutation, resulting in tumor dedifferentiation." (PMID 35865459, 2022). "The median tumor enhancement score was 1.5 (IQR 1; 2.5) in NF1 + OPG and 2 (IQR 2; 4) in spOPG patients at first measurement." (PMID 34994964, 2022).
tumor (continued). "As our studies were performed in Nf1+/+ mice, our findings provide new insight into sporadic MPNST biology by virtue of recapitulating their tumor microenvironment." (PMID 35571990, 2022). "However, we could not exclude that NF1 was lost in the tumor via a compound heterozygous mutation or microdeletion since the fragmented tumor DNA at our disposal did not allow these types of investigations." (PMID 35456261, 2022). "DAPI+ nuclei containing detectable, activated (nuclear) p65 represented 2.22% ± 0.33% of tumor cells, and, of GFP+Nf1-mutant SCs, 7.12% ± 1.15% of mutant SCs do so." (PMID 36134665, 2022). "At the top of the table are given the states of the integrin, RTK, and Wnt receptors, while the signals from E‐cadherin and tumor suppressors, APC and NF1, are indicated at the right and left of the table, respectively." (PMID 35132721, 2022). "NF1 and STAG2 were the most strongly downregulated candidates with well-established tumor suppressor functions." (PMID 34967922, 2022). "The potential role of Evi-2 in murine neoplastic disease and the map representation of the human homolog indicates a possible role for EVI2 in NF1." (PMID 37533672, 2022). "To confirm that apoptosis occurs at a higher rate in the LV-miniMg-∆MEF3/NF1-HSV sample group compared with the LV-∆miniMg-HSV control, we performed TUNEL staining on cryosections from excised tumours." (PMID 32973362, 2021). "Future studies focusing on the mechanistic relationship between radiation doses and tumor aggressiveness, as well as the influence of germline backgrounds, may provide clearer insights on the biology of radiation-induced malignant transformation in NF1 context." (PMID 34131650, 2021). "Utilizing genetically engineered mouse models of tumor specific manifestations of both NF1 and NF2, and appropriate cell lines, the preclinical consortium has focused on screening and testing potential therapeutic options of reach tumor type." (PMID 34885143, 2021). "This sexual dimorphism has been explored in Nf1 mutant mice, where only female mice presented reduced visual acuity from their OPG despite equal tumor volumes and proliferative indices." (PMID 34809690, 2021). "Transcriptomic profiling revealed that a macrophage/microglia-rich tumor microenvironment is key for the development of the MSC molecular subtype, which is further facilitated by NF1 depletion." (PMID 32765498, 2020). "Copy number alterations were retained across several tumor-organoid pairs include CDKN2A, ERBB2, NF1, and SNX31." (PMID 32774159, 2020). "A comparison between the miRNA profiles observed in the sporadic MPNST and the NF1-derived MPNST revealed many differentially expressed miRNAs emphasizing these tumor types have a different etiology and possibly a different biology." (PMID 32076030, 2020). "Tumour suppressor genes, including PTEN and NF1, were detected at high amplification peaks with high PIEZO1 expression." (PMID 32999349, 2020).
tumor (continued). "We also found that in patients with NF1-MPNST with lung metastasis, MSI2 was highly expressed in comparison to primary tumours, where CAV1 expression was the opposite; CAV1 expression was low in lung metastases and high in primary tumours." (PMID 32606289, 2020). "NF1 transcript levels were significantly lower in both the primary and matched TK-RIG915 PDX tumours compared to both reference sets, consistent with other tumours in the reference cohorts that had homozygous deletion of NF1." (PMID 33053751, 2020). "Because the prognosis for patients with NF1-MPNST is very low, it is important to improve the treatment options for these tumours." (PMID 32606289, 2020). "In this study, we found that MBZ inhibited the growth of NF1-related MPNST cells in vitro and substantially delayed tumor formation in NPcis mice when initiated 60 days after birth, without overt disease." (PMID 32650362, 2020). "NF1 and NF2 have been critical models in the study of cancer, with each yielding numerous insights into the biology of neoplasia and genetic inheritance." (PMID 31161239, 2020). "Second, silencing NF1/Nf1 in doxorubicin‐treated SW1573 cells as well as doxorubicin‐treated LKR10 and LKR13 clones resulted in significantly greater subcutaneous tumor volumes across all three models." (PMID 31036704, 2019). "The BRAF, NRAS and NF1 driver alterations all activate the mitogen‐activated protein kinase (MAPK) pathway and generally occur at the earlier stages of tumour evolution." (PMID 30511391, 2019). "The results showed that in many cases, chemoresistant tumours inactivated tumour suppressor genes (RB1, NF1, RAD51 paralog B (RAD51B), PTEN) through gene breakage." (PMID 31146417, 2019). "HMGA2 knockdown regulates autophagy via MSI2-Beclin1 interactions to inhibit NF1 MPNST growth, revealing potential therapeutic targets for these untreatable tumours." (PMID 31053152, 2019). "miR-34a is a tumor suppressor downregulated in MPNSTs, as shown by in vitro studies using the cell lines MPNST-14 (NF1 mutant) and MPNST-724 (from a non-NF1 individual)." (PMID 31694342, 2019). "Correlation studies with clinical variables confirmed that NF1 status, tumor size (>10 cm), and MVD in tumor periphery (higher tercile) lead to a significant reduction of the OS." (PMID 30735009, 2019). "Both Neurofibromatosis 1 and 2 (NF1 and NF2) are disorders characterized by the formation of tumours of the peripheral and central nervous system, primarily affecting cells of neural crest origin." (PMID 31730023, 2019). "Altogether, these data demonstrate that HMGA2 is vital for NF1 MPNST cell survival and that repression of HMGA2 leads to tumour cell apoptosis." (PMID 31053152, 2019). "MiR-10b overexpression accelerated PCC proliferation and tumor growth; miR-10b enhanced the stimulatory effects of EGF and TGF-β on cell migration and EMT, decreasing the expression of RAP2A, EPHB2, KLF4 and NF1." (PMID 29254283, 2017). "Altogether, our studies demonstrate frequent disruption of MAX tumour suppressive roles during early progression of KIT-mutant, PDGFRA-mutant and NF1-mutant GISTs." (PMID 28270683, 2017). "The second cluster contained the kinase signalling subgroup including the RET, NF1, TMEM 127 and MAX mutant tumours." (PMID 29166454, 2017).